FTH1 (ferritin heavy chain 1)
Diseases named in the same sentence as FTH1 in open-access papers (continued):
Sharing a sentence is not in itself a finding about the gene and the disease.
tumor (continued). "Immunohistochemistry staining of tissue microarrays also demonstrated a trend toward FTH1 accumulation from primary to end-stage tumours in individual patients." (PMID 40998801, 2025). "Sh‐YTHDF2 and DNase I inhibited GPX4, SLC7A11, and FTH1 expression in the tumour, while increasing ACSL4 and PTGS2 levels and had a superimposed effect." (PMID 39865544, 2025). "Compared with the single PEG3 promoter, the chimeric construct not only ensured specificity of FTH1 expression in tumor tissues but also significantly enhanced the expression efficiency of FTH1 at different levels." (PMID 40723232, 2025). "The study of FTH1 is becoming a promising target of NSCLC because of its function as a tumor-suppressor gene." (PMID 40538534, 2025). "The combination of JQ1/FTH1 silencing promoted ferroptosis, reducing tumor growth in cells that showed a poor response to JQ1 alone." (PMID 40652527, 2025). "FTH1 acts as a tumor suppressor in NSCLC through the modulation of iron metabolism and the apoptotic pathway." (PMID 40538534, 2025). "Silencing FTH1 leads to increased tumor growth, migration, and chemoresistance, along with upregulation of oncogenes like c-MYC and G9a." (PMID 41378310, 2025). "In clinical NB cases, higher OGT, FOXC1, ASNS, GPT2, CBS, or FTH1 levels are correlated with worse survival, while lower ecircOGT or OGT-570aa expression is associated with tumor progression." (PMID 40416363, 2025). "Numerous studies have highlighted the crucial value of the heavy chain of ferritin (FTH1) as a key regulator of iron metabolism and a suppressor of ferroptosis, intimately tied to the tumor immune microenvironment (TIME)." (PMID 38281198, 2024). "In animal models, FTH1 knockdown paralleled the in vitro results, demonstrating suppressed tumor growth and suggesting an enhancement of the therapeutic effect of DFX." (PMID 39294443, 2024). "Inhibiting FTH1-related signaling pathways appeared to be a potential strategy to counteract tumor immunotherapy resistance." (PMID 38281198, 2024). "We also confirmed the rescue effect of FTH1 in vivo: FTH1 knockdown in SUIT-2 cells suppressed tumor growth, whereas the restoration of FTH1 expression rescued its tumor-suppressive effect." (PMID 39294443, 2024). "Next, we unveiled the FTH1 expression in tumor cells and various immune and stromal cells in several solid cancer types, namely CESC, ESCC, HCC, and GC." (PMID 38281198, 2024). "For all we know, this research is the first to systematically investigate the role of FTH1 in tumor immunology from a pan-cancer perspective." (PMID 38281198, 2024). "Currently, selective delivery mechanisms, such as antibody‒drug conjugates (ADCs) and ligand-directed systems, present a viable option to deliver FTH1 inhibitors by recognizing tumor-specific markers, thereby sparing normal cells." (PMID 39294443, 2024). "Firstly, to comprehensively exhibit the expression details of FTH1 in tumor and adjacent samples, we found high FTH1 expression in various tumor cell lines, particularly in the ampulla of Vater, ovary, cervix, and thyroid according to the CCLE dataset." (PMID 38281198, 2024). "In KRAS-mutant SUIT-2 cells, FTH1 knockdown led to significant decreases in cancer cell viability via G2/M cell cycle arrest in vitro as well as tumor growth suppression in the SUIT-2 xenograft model in vivo." (PMID 39294443, 2024). "Single-cell sequencing analysis and multiplex immunofluorescence staining techniques are applied to observe FTH1 co-expression on both tumor and immune cells." (PMID 38281198, 2024). "We also verified the expression of FTH1 on various macrophages and tumor cells by multiplex immunofluorescence staining." (PMID 38281198, 2024). "The critical role of FTH1 in tumor immunity underscores its potential as a therapeutic target to enhance the benefits of immunotherapy for a broader patient population." (PMID 38281198, 2024).
tumor (continued). "FTH1 was highly expressed in M1 macrophages and tumor cells in various cancers, which was also expressed in CD163+ M2 macrophages in ESCC and HCC." (PMID 38281198, 2024). "We confirmed the successful establishment of stable FTH1-knockdown cells and the tumor-suppressive effects of FTH1 in SUIT-2 cells." (PMID 39294443, 2024). "Activation of NFE2L2 in mouse xenograft tumour models also enhanced the expression of FTH1 and GPX4 and decreased the expression of TFRC to some extent." (PMID 38685674, 2024). "Consistent with the in vitro results, FTH1 knockdown in SUIT-2 cells suppressed tumor growth: shFTH1 mice demonstrated significantly slower tumor growth on days 9 and 11 than did Scr mice and on days 7, 9, and 11 than did Void mice." (PMID 39294443, 2024). "While our bioinformatics methods have shed light on these associations, further basic and clinical studies are crucial to fully elucidate the mechanisms of FTH1 in tumor immunity." (PMID 38281198, 2024). "For example, upregulation of the FTH1 gene inhibits the destructive effect of ferroptosis on intracellular microbiomes, resulting in a microbial state that is more favorable for tumor metastasis." (PMID 36672459, 2023). "Taken together, these findings suggest that when the FtH1 upregulation associated with the 2D to 3D transition is prevented, PEO1 cells significantly reduce their ability to generate tumor spheroids." (PMID 38033861, 2023). "Due to the intersection of iron metabolism and tumor-suppressive pathways, it is likely that tumor-suppressive pathways are affected in conditions of altered expression of FTH1." (PMID 37894914, 2023). "As research has shown that FTH1 mediates a tumor suppressor role in PCa, it would be prudent at some point to examine the pseudogene-miRNA network." (PMID 37894914, 2023). "Taken together, our findings indicate that NRF2 controls ferroptosis through FTH1, while PPI induces cell ferroptosis and tumor repression via suppressing NRF2/FTH1 pathway." (PMID 37081971, 2023). "Concerning the regulation of iron metabolism in iron-rich culture media, HEY tumor spheroids continue to increase FtH1, further reduce CD71, and also increase FPN expression levels." (PMID 38033861, 2023). "At present, the research of FTH1 in tumor pathogenesis mainly exerts its functions by affecting iron metabolism." (PMID 38025726, 2023). "Specifically, tumors with high expression of genes such as FTH1, EGLN1, and BCPB1 had more microbiomes associated with tumor metastasis." (PMID 36672459, 2023). "In this study, the MMP‐2‐sensitive peptide and flexible peptide were inserted between the FTH1 and TmSm proteins, enabling the release of the TmSm protein at the tumor site." (PMID 35600646, 2022). "The fact that tumor volume in the FTS/YM155 NC group showed a greater decrease than that in the other groups suggested that the FTH1 NC delivery platform greatly enhanced the antitumor effect." (PMID 35600646, 2022). "This is mainly due to incomplete knowledge of the overall scenario in which FTH1 and its partners interact to promote tumor progression." (PMID 36361777, 2022). "A smart example of this approach was the MRI-mediated identification of tumor transformation of transplanted stem cells using a ferritin heavy chain (FTH1) reporter under the control of a promoter of the tumor-specific gene progression elevated gene-3 (PEG3)." (PMID 36291103, 2022). "It was found that the expressions of GPX4 and FTH1 in A549 xenograft tumours were significantly reduced by irradiation, which was reversed by the upregulation of ANGPTL4." (PMID 36050447, 2022). "FTH1 down-regulation is likely an adaptive response, as there is evidence to suggest that FTH1 expression is innately tumor suppressive." (PMID 35447901, 2022). "Based on these deductions, we here knock down five additional genes related to iron and redox homeostasis (NRF2, GPX4, SLC7A11, FSP1, FTH1), for further improving the anti-tumor efficacy of GIFT." (PMID 36329436, 2022).
tumor (continued). "Increasing FTH1 expression would likely restore its function as an iron regulator and tumor suppressor by sequestering oncogenic miRNAs, relieving it of oncogenic miRNA inhibition." (PMID 35447901, 2022). "The aim of the experiment was to explore the feasibility of using the tumor-specific promoter PEG3 to drive the expression of the reporter gene FTH1 for MRI detection of the malignant transformation of bone marrow-derived MSCs." (PMID 33980305, 2021). "We developed a novel MRI model based on FTH1 reporter gene expression driven by the tumor-specific PEG3 promoter." (PMID 33980305, 2021). "To solve this problem, we modified the reporter gene FTH1 by adding the tumor-specific promoter PEG3 upstream and successfully transferred the modified reporter gene into stem cells with a recombinant lentivirus." (PMID 33980305, 2021). "In conclusion, we developed a novel reporter gene-based MRI monitoring system for the detection of the malignant transformation of stem cells by modifying the genetic reporter FTH1 to be under the control of the tumor-specific promoter PEG3." (PMID 33980305, 2021). "The inference that FTH1 is a tumor suppressor in BCa is also consistent with the observation that reduced c‐MYC and/or G9a increased the sensitivity of BCa cells to anticancer drugs." (PMID 34551213, 2021). "Although the miR-21-responsive FTH1 gene reporter system was proven to have potential for the MRI assessment of miR-21 function in tumor cells, there are several drawbacks in this study." (PMID 34804934, 2021). "To determine the source(s) of the correlation between FTL and FTH1 levels and Immune Score in most cancers, we examined correlations between expression and tumor-infiltrating cell subsets using MCP-counter, TIMER, and TIMINER." (PMID 33864445, 2021). "To clarify the potential role of FTL and FTH1 in tumor immunity, we next examined correlations between the expressions of FTL and FTH1 and 47 distinct immune-related markers using Pearson Correlation Coefficient analysis." (PMID 33864445, 2021). "The reporter gene ferritin heavy chain (FTH1) was modified by adding a promoter from the tumor-specific gene progression elevated gene-3 (PEG3) and transduced into MSCs to obtain MSCs-PEG3-FTH1." (PMID 33980305, 2021). "Concerning BCa, while several previous studies have suggested that increased FTH1 expression associates with increased resistance to chemotherapy, others have shown that FTH1 can serve as a significant tumor suppressor in BCa." (PMID 34551213, 2021). "FTH1 acts as a tumor suppressor in non-small cell lung cancer, breast cancer, and ovarian cancer and as a tumor promoter in metastatic melanoma cells." (PMID 33260500, 2020). "Ovarian cancer samples had elevated FTL and FTH1 detected in the cytoplasm and nucleus compared to benign tissue and increased with tumor grade." (PMID 32328462, 2020). "In two separate studies downregulation of FTL with an antisense construct and FTH1 with shRNA in melanoma cells inhibited proliferation and invasion in vitro and tumor growth in vivo." (PMID 32328462, 2020). "Another field that needs further investigation is the link between the FTH1/pseudogenes networks, the miRNAs involved in these networks, and other tumor genes." (PMID 33260500, 2020). "Repression of nitrogen fixation 1 (NFS1) predisposes tumor cells to ferroptosis by activating the iron-starvation response via stabilizing TFRC transcription and inhibiting ferritin heavy chain 1 (FTH1) translation." (PMID 33425217, 2020).
tumor (continued). "FTH1 also serves as a novel marker for macrophages, and FTL is a prognostic marker in tumor-associated macrophages, along with CD163." (PMID 28957348, 2017). "Additionally, the Ki67 index decreased in FTH1‐knockdown tumours and increased in FTH1‐overexpressing tumours." (PMID 40504108, 2026). "Functional experiments using FTH1‐knockdown/−overexpressing HCC cell lines and xenograft models demonstrated that FTH1 enhances proliferation, migration, and tumour growth by upregulating CYP1A1/CYP1A2 in the tryptophan pathway, thereby increasing the synthesis of 6‐hydroxymelatonin (6‐HMT)." (PMID 40504108, 2026). "Additional IHC confirmed that the Ki67 index was elevated in tumours with high FTH1 scores." (PMID 40504108, 2026). "In summary, for the first time, our data suggest that FTH1 silencing may serve as an effective anti‐tumor strategy to enhance the activity of JQ1, acting to overcome the chemotherapy resistance in more aggressive NSCLCs." (PMID 40652527, 2025). "Similarly, in the context of tumor immunotherapy resistance, FTH1 contributes to the development of an inhibitory tumor immune microenvironment, which facilitates resistance to anti-PD-1/L1 immunotherapy by regulating immune cell infiltration and activation." (PMID 39941157, 2025). "Meanwhile, lower level of FTH1 was also observed in SH3GL1 knockout xenograft mouse tumour tissues." (PMID 40038872, 2025). "However, more investigation is needed to explore how FTH1 exerts its tumor-suppressive role at the molecular level in the current context." (PMID 40538534, 2025). "Given its significance as an iron metabolism regulator and ferroptosis suppressor, FTH1 may intricately link with the tumor immune microenvironment and responses to immunotherapy." (PMID 38281198, 2024). "However, mRNA expressions of FTH1 in tumor tissues were significantly alleviated in 1‐D‐6‐G‐administered xenograft mice in a dose‐dependent manner." (PMID 39402821, 2024). "Our comprehensive analyses may offer valuable insights into the role of FTH1 in tumor immunotherapy." (PMID 38281198, 2024). "Additionally, our study demonstrated that deferasirox, an oral iron chelator, significantly diminishes cell viability and tumor growth in KRAS-mutant PDAC by targeting FTH1-mediated pathways and altering the PYCR1/PRODH expression ratio." (PMID 39294443, 2024). "GPX4 and FTH1 are the symbols of iron death occurring in tumor cells." (PMID 38345573, 2024). "Additionally, the mean tumor weight was lower in the FTH1 knockdown group (0.180 g) than in the control group (0.532 g for the SUIT-2 group and 0.604 g for the Scr group) and greater than that in the FTH1 rescue group (0.334 g)." (PMID 39294443, 2024). "We found that FTH1 was highly expressed in tumor cells and macrophages." (PMID 38281198, 2024). "We observed that FTH1 exhibited higher expression level in the macrophages and tumor cells." (PMID 38281198, 2024). "It is obvious that FTH1 is significantly co-expressed in tumor cells and immune and stromal cells." (PMID 38281198, 2024). "Notably, we found that FtH1 silencing is sufficient to reduce the generation and expansion of tumor spheroids; however, it is unable to sensitize PEO1 cells to ferroptosis, and cell viability results untouched." (PMID 38033861, 2023). "The overexpression of FTH1 in tumor tissues may be a good indicator of its cancer-promoting function." (PMID 38025726, 2023). "The upregulation of FTH1 in tumor cells or immune cells, for example, may contribute to a reduction in the clearance of bacteria by inhibiting ferroptosis." (PMID 36672459, 2023). "In light of FTH1’s apparent involvement in oncogenesis, its expression in PCa may be of greater significance than currently realized in terms of its influence on tumor suppression." (PMID 37894914, 2023). "Recent research indicates that the FTH1 pseudogenes play a key role in tumor suppression." (PMID 37894914, 2023).
tumor (continued). "Indeed, PEO1 3D tumor spheroids strongly upregulate FtH1 while HEY 3D tumor spheroids only moderately increase it." (PMID 38033861, 2023). "In contrast, the IOL diet might have led to increased levels of LIP in tissues because of upregulated levels of hepcidin and DMT1, and weakened defenses against increased oxidative stress with decreased FTH1 levels, leading to tumor cell death." (PMID 35631174, 2022). "To determine whether ferritinophagy is required for 4OI-mediated tumor suppression, we assayed the level of FTH1 in control and NCOA4-knockdown Y79-CR cells." (PMID 35654783, 2022). "This pattern of gene expression would rearrange iron-trafficking and storage proteins in a way that is unfavorable to cancer survival, through an increase in FTH1-mediated tumor suppression and iron sequestration, while diminishing the ability of iron uptake through the TfR1 importer." (PMID 35447901, 2022). "On the other hand, reduction in FTH1 may lead to the accumulation of free iron and subsequent increase in ROS which in turn can promote tumour metastasis and immune suppression." (PMID 34211054, 2021). "Data presented here clearly show that FTH1 is a significant tumor suppressor in BCa cells." (PMID 34551213, 2021). "The correlation analysis of the expression of GSTA2 and the identified ROS-associated genes using the LIHC database in the GEPIA web server revealed that the expression level of GSTA2 was significantly correlated with ALB, TPO, APOE, MBL2, and FTH1 in the tumor tissues." (PMID 34290233, 2021). "This is because tumours release FTH1 to induce an immunosuppressive microenvironment by re-programming dendritic cells so they induce production of the anti-inflammatory cytokine IL-10 from regulatory T cells, hence, allowing the tumour to escape immune surveillance." (PMID 34211054, 2021). "Additionally, we analyzed the correlation of FTH1 expression with infiltrating immune cells and tumor purity." (PMID 34965856, 2021). "To this end, we analyzed datasets from The Cancer Genome Atlas (TCGA), a landmark cancer genomics database started in 2006, and additionally employed a number of bioinformatics tools to assess the relationship between tumor FTL and FTH1 levels and tumor infiltration by various immune cell subsets." (PMID 33864445, 2021). "The observation that FTH1 expression increases in response to chemotherapy raised the question of whether inhibition of FTH1 can render tumor cells more resistant to chemotherapy." (PMID 34551213, 2021). "Importantly, these functional mutations affected genes that belong to cancer-related pathways and include the oncogenic FTH1 and tumor-suppressive MECOM." (PMID 34244513, 2021). "The reduction in FTH1 expression observed in the IV treatment group may promote immune evasion by tumours." (PMID 34211054, 2021). "Additionally, RM-3-22 upregulated FTH1, a tumor suppressor, reinforcing its anticancer potential." (PMID 40538534, 2025). "Furthermore, FTH1 is highly expressed in Tregs and supports forkhead box protein 3 (Foxp3) demethylation and Treg stability, ultimately affecting autoimmunity and anti‐tumour response." (PMID 40045458, 2025). "To test our hypothesis, we verified the vulnerability of FTH1‐silenced tumor cells to JQ1, a pan‐BET inhibitor, initially identified as a BRD4 inhibitor, and then, it has been shown to inhibit multiple BET protein members due to the well‐preserved bromodomain sequence." (PMID 40652527, 2025). "When grown in a non-iron rich culture medium, FtH1 knockdown causes a significant reduction of both number (from 664 to 286, *p-value <0.05) and size (from 116.1 μm to 88.8 μm, ****p-value <0.0001) of tumor spheroids." (PMID 38033861, 2023). "However, the role of FTH1 in tumor development has recently been reported." (PMID 34853622, 2021). "Interestingly, FTH1 released by tumor cells has immunosuppressive effects of lymphocytes." (PMID 32328462, 2020).